GATA3 (GATA binding protein 3)
Diseases named in the same sentence as GATA3 in open-access papers (continued):
Sharing a sentence is not in itself a finding about the gene and the disease.
cancer (continued). "This importance is apparent from the early embryonic lethality following germline Gata3 deletion, with embryos displaying a number of phenotypes, and from the fact that Gata3 has been implicated in several cancer types." (PMID 30463912, 2018). "In a larger pan-cancer set of 4128 TCGA exomes with expression profiling, we identified mutational correlation with expression for additional elements (e.g., near GATA3, CDC6, ZNF217, and CTCF transcription factor binding sites)." (PMID 29354286, 2018). "A Th2 (GATA3>T-bet) predisposition has been reported in different cancer entities and metastatic lymph nodes and was found to be associated with cancer recurrence, progression and poor survival." (PMID 28005163, 2017). "On the contrary, strong expression of GATA3 was associated with progression and poor cancer-specific survival in muscle-invasive bladder tumors." (PMID 28005163, 2017). "It is a well-known fact that GATA3 expression is associated with disease free survival and can reverse the cancer metastasis." (PMID 28423671, 2017). "The up-regulation of GATA3 has been also associated with cancers some being of hematopoietic origin." (PMID 28379958, 2017). "The outcomes of mutations at the far carboxyl terminus of GATA3, an abundant class of cancer-specific mutants, are currently understudied." (PMID 26922637, 2016). "It is also conceivable that the cancer-specific mutations in GATA3 alter co-factor recruitment and interaction (either positively or negatively) leading to novel or impaired pioneering functions." (PMID 26922637, 2016). "To investigate what functional aspects of cancer cells specifically correlate with GATA3-ext mutations, we calculated the association of this mutation class with gene expression levels without performing segmentation." (PMID 27588951, 2016). "This suggests that at least one copy of wild-type GATA3 is required for viability in these cell lines, which is in accordance with the findings from human cancer samples but complicates the introduction of a mutated version for in vitro models." (PMID 27588951, 2016). "In addition, a comparison with GATA3 expression was conducted to further evaluate the diagnostic potential of Upk1a and Upk1b for identifying cancers of urothelial origin." (PMID 37777995, 2024). "We did not observe any significant difference in the expression level of T-cell-associated transcription factors among precancer and cancer groups; however, GATA3 (TH2 associated) showed an increased expression level, although not significant, in cancer samples." (PMID 37409975, 2023). "Nearly half of protein-coding associated mutations of the Top1 mutated gene GATA3 (128/261) occurred in BRCA while the protein-coding associated mutations of 9 other genes tened to be evenly distributed across all the cancer types with a major pattern of missense mutation." (PMID 37917664, 2023). "GATA3 encodes a protein that is important regulator to T-cell development and related to cancer." (PMID 37546388, 2023). "Loss of GATA3 occurs frequently in BC and is associated with the aggressive growth and spread of the disease, and studies have demonstrated that overexpressing SEMA3B in GATA3-deficient BC cells replaces some aspects of GATA3 function, resulting in increased cancer cell survival." (PMID 37685898, 2023). "The systemic analysis defined those GATA3 mutations as cancer drivers." (PMID 35154280, 2022). "In addition, high GATA3 was more likely to be a luminal subtype, which meant it was less susceptible to cancer immunotherapy and neoadjuvant chemotherapy but more sensitive to targeted treatments." (PMID 35647011, 2022). "The rest of GATA3 had an antagonistic association with survival depending on the cancer types." (PMID 34301206, 2021).
cancer (continued). "Therefore, we performed a functional knockdown screen of 92 cancer associated transcription factors and identified GATA3, SPDEF, IRF9, and YY1 as candidate transcriptional activators/repressors for APOBEC3B gene expression." (PMID 32934779, 2020). "GATA3 has been discovered to be linked with the development and invasion of cancer cells." (PMID 31791342, 2019). "Furthermore, a crosstalk between CD4+, GATA3+ T cells and cancer-associated fibroblasts was identified that resulted in greater infiltration of Th2 T cells and decreased patient survival." (PMID 31068602, 2019). "The high frequency suggests that GATA3 mutations are cancer “drivers”." (PMID 29535312, 2018). "Recently, GATA-2 and GATA-3 were found to be associated with tumorigenesis in various cancers." (PMID 27528231, 2016). "Work has suggested that GATA3 may act as a differentiation factor within breast cells that, when lost, typically through mutation, allows cancer progression." (PMID 24887547, 2014). "Considerations of mutational modifications demonstrate how a GATA3 positive cancer may actually produce a distinct clinical phenotype." (PMID 25410484, 2014). "That the combination of Upk1a/Upk1b and GATA3 resulted in an even stronger association with patient survival and that this link was still completely limited to pT4 cancers may suggest that IHC panels identifying luminal type pT4 carcinomas may have clinical utility in the future." (PMID 37777995, 2024). "Collectively, it has been indicated that GATA3 is a major driver of epigenomic reprogramming that can directly influence the activity of oncogenes, suggesting a critical pathway through which inherited genetic variations might impact the risk of cancer." (PMID 39768217, 2024). "Since GATA3 IHC is currently used in routine diagnostic practice as a surrogate marker for breast and urothelial origins of carcinomas of unknown primary, this should be straightforward, however, standardized methods with a univocal and reproducible cutoff are needed." (PMID 33800667, 2021). "However, limited research has focused on what causes the downregulation of GATA3 in cancers." (PMID 31856849, 2019). "The results identify a new molecular link between cell cycle regulators and regulation of differentiation genes (such as GATA3 and FoxA1) that offers insights also into how over-expression of FoxM1 might be playing a causal role in maintaining poorly differentiated state of cancer cells." (PMID 28387346, 2017). "Using BRCA data from the TCGA database, further analysis of GATA3 expression across multiple cancer types showed significant differences, with a notable upregulation in BC patients." (PMID 40881878, 2025). "The data suggested that YTHDF2 binds with m6A methylated GATA3 mRNA and recruits Dis3L2 to induce its degradation in cancer cells." (PMID 39800682, 2025). "On IHC level they found that although TRPS1 and GATA3 expression were comparable in hormone-positive and HER2neu-positive cancers, however the expression of TRPS1 was higher in TNBC, particularly metaplastic carcinoma compared with GATA3 (86% vs. 21%)." (PMID 40025593, 2025). "By comparison, BANKSY captured a pattern involving GATA3 positive cancer cells (cluster 1), but from its output it is not apparent how they are organized with respect to other cell classes." (PMID 40307222, 2025). "The GATA3–METH and GATA3–LOFDEL cancer subtypes are also both significantly depleted in genes associated with luminal-A and luminal-B molecular subtypes, consistent with their aggressive profiles." (PMID 40585280, 2025). "That only 6% of cancers with strong GATA3 staining harbored a high-level amplification further demonstrates that gene copy number gains are not the major cause for increased GATA3 expression." (PMID 39979991, 2025). "It aligns with previous studies linking GATA3 expression to poor prognosis in other cancers, such as breast and bladder." (PMID 40856420, 2025).
cancer (continued). "This indicated that YTHDF2 was responsible for m6A induced degradation of GATA3 mRNA in cancer cells." (PMID 39800682, 2025). "The fraction of tumors with GATA3 high-level amplification was higher in pT2-4 carcinomas (5.4%) than in (all) pTa tumors (pTa 2.4%; p < 0.0001 for pTa vs. pT2-4) but it was lower than in pTa G3 tumors (pTa G3 12.1%; p < 0.0001 for pTa G3 vs. pT2-4)." (PMID 39979991, 2025). "Our study demonstrated a higher sensitivity of TRPS1 expression in establishing carcinoma of breast origin compared with GATA3 and SOX10, consistent with previous reported studies." (PMID 40025593, 2025). "GATA3 is a sensitive marker commonly used to evaluate for carcinomas of urothelial and breast origin in the metastatic setting." (PMID 40691018, 2025). "An increased number of GATA3 gene copies were detectable in 218 (9.9%) of the 2,213 analyzable carcinomas, including 44 (2.0%) with GATA3 elevation, 71 (3.2%) with low-level amplification, and 103 (4.7%) with high-level amplification." (PMID 39979991, 2025). "Our study demonstrated a higher sensitivity of TRPS1 in establishing carcinoma of breast origin compared with GATA3 and SOX10, consistent with previous reported studies." (PMID 40025593, 2025). "The sensitivity and specificity of TRPS1 in determining carcinoma of breast origin were compared with those of GATA3 and SOX10." (PMID 40025593, 2025). "For example, the fraction of GATA3 high-level amplificated carcinomas increased from pTa G2 low (0%), to pTa G2 high (2.4%), and pTa G3 (12.1%; p < 0.0001)." (PMID 39979991, 2025). "GATA3, an immunostain considered highly sensitive for carcinomas of breast origin, showed strong and diffuse nuclear staining." (PMID 41216105, 2025). "GATA3 is a defining marker for luminal cancers and an important regulator of luminal differentiation." (PMID 39049124, 2024). "A recent study that analyzed the T cells in pan cancers has also shown the presence of TH2-like TREGs that were marked by a higher expression of GATA3." (PMID 38501302, 2024). "Nonetheless, the mechanisms behind GATA3 downregulation leading to switching off the tumor suppressor genes in most cancers remain elusive." (PMID 39768217, 2024). "•PIK3CA and GATA3 were the main cancer driver genes in luminal samples, and candidate drivers were GRHL2 and SMURF2." (PMID 39208653, 2024). "In luminal samples, PIK3CA and GATA3 were the main cancer drivers, and other drivers were GRHL2 and SMURF2." (PMID 39208653, 2024). "GATA3 overexpression was correlated potentially to the chromosomal instability and vulnerability to translocations that take place in earlier stages of cancer onset." (PMID 39768217, 2024). "GATA3-/FOXA1- was associated with shorter Disease-Free Survival (DFS) (P=0.001) and Cancer-Specific Survival (CSS) (P<0.001) than other combination groups." (PMID 38425344, 2024). "Cancer patients with Sh infection also had fewer cells expressing GATA3, which is important to generate an optimal Th2 immune response." (PMID 39250522, 2024). "Immunohistochemical staining was strongly positive for CK7, a cytokeratin that supports a diagnosis of carcinoma, and for mammaglobin and GATA-3, markers that support a diagnosis of breast carcinoma." (PMID 39022491, 2024). "GATA3 immunohistochemistry has been described as a highly sensitive marker in determining carcinomas of breast and urothelial origin." (PMID 39118796, 2024). "Differently from NST carcinomas, lobular tumors more often exhibit mutations in ARID1A, PTEN, FOXA1, and Her2 genes and less frequently in GATA3 and MAP2K4 genes." (PMID 38015260, 2024). "Further mutations in luminal NST carcinomas involve genes such as ESR1, (especially a progression mutation after hormonal therapy), FGFR1, MDM4, AKT1, and GATA3." (PMID 38015260, 2024). "GATA3 and Upk1a/Upk1b immunostaining showed a strong statistical correlation in our 1596 pT2-4 carcinomas with data on all three markers (p < 0.0001)." (PMID 37777995, 2024).
cancer (continued). "Unlike FATWO, which lacks a specific anatomical location or a sieve-like microscopic pattern, mesonephric carcinomas typically exhibit strong positivity for GATA-3 in immunohistochemical testing." (PMID 40034930, 2024). "Excluding the spindle cell subtype, all metaplastic carcinomas in this cohort were positive for either pankeratin, GATA3 or SOX10." (PMID 37306115, 2024). "A more sensitive marker, GATA3, has been found to be positive in both primary and metastatic breast cancer, although GATA3 is multispecific in different types of cancer cells." (PMID 36281523, 2023). "The survival curves were stratified based on the expression of GATA-3 and analyzed only in malignant tumours." (PMID 37483298, 2023). "KMT2D and GATA3 were uniquely identified in African Americans as cancer drivers reported in TCGA data, whereas PIK3CA, MAP3K1, CDH1, and MUC6 were identified in Caucasians." (PMID 37454130, 2023). "Budina reported that the luminal subtype with GATA3 expression is the predominant phenotype in T1 cancers." (PMID 37629741, 2023). "For example, GATA3 mutations connected with reduced TMB in BRCA and increased TMB in five other cancer types." (PMID 36911742, 2023). "For example, zinc finger protein Nrf2 can promote cancer cell metastasis and proliferation by regulating the oxidative stress response, while GATA3 can inhibit cancer cell angiogenesis and invasion." (PMID 38033582, 2023). "Four cancer type-specific molecular markers (PanCK, GATA3, HER2, and HE4), as well as CD13, were used for prognostication and recurrence detection, along with downstream genomic analysis." (PMID 36768623, 2023). "GATA binding protein 3 (GATA3) is a highly conserved transcription factor that plays a pro‐ or anticancer role in cancer progression." (PMID 36468944, 2023). "This is indicated in cancer cells that have GATA3 depletion, where there is decreased ESR1-binding affinity, which, in turn, decreases the expression of FOXA1." (PMID 36836779, 2023). "The results demonstrated that complex adenoma or simple carcinoma cells exhibited lower levels of GATA-3 expression, while considerably higher levels were expressed in complex or mixed carcinoma cells." (PMID 37483298, 2023). "The results of the present study confirm the correlation between the most significant expression of GATA-3 and cell differentiation, given its overexpression in benign tumors and well-differentiated carcinomas." (PMID 37483298, 2023). "GATA-3 and estrogen receptor (ER) expression were higher in benign and well-differentiated carcinomas than in aggressive tumors, which showed greater Ki-67 expression." (PMID 37483298, 2023). "Canine benign tumors or well-differentiated carcinomas exhibited intense and diffuse GATA-3 staining patterns of by immunohistochemistry, while canine aggressive tumors showed only mild and scattered results or the absence of stain." (PMID 37483298, 2023). "As a result, GATA3 expression is downregulated, cancer and metastasis are promoted, and normal hepatocytes lose their stability as a result of the HuR-GATA3 interaction." (PMID 36467404, 2022). "This shows that FOXA1 and GATA3 do maintain hypo-methylated regions in cancer compared to normal cells at a subset of their binding sites." (PMID 35331302, 2022). "The last PCR4 fragment (141 bp) is inside the intron 10, located after the splicing site and contained consensus sequence target of GATA3 (chr20:36,763,169-36,763,309 GRCh37/hg19), also recognized by a RNApol II site in other type of cancer." (PMID 34975314, 2022). "Last we tested the consequence of TF binding on DNA methylation patterns by deleting FOXA1 or GATA3 in HCC1954 cancer cells." (PMID 35331302, 2022). "The study found that 19/21 cases expressed GATA3 in over 25% of the cancer cells, and five of these 19 co-expressed KRT5/6." (PMID 35406463, 2022).
cancer (continued). "Gene expression and protein abundance for EpCAM/EpCAM, ESR1/ER, PGR/PGR, GATA3/GATA3 were detected in cancer epithelial cells." (PMID 36307545, 2022). "We initially used pan-cancer analysis to analyze the expression pattern and immunological function of GATA3 with data gathered from the TCGA (The Cancer Genome Atlas)." (PMID 35647011, 2022). "Similar huge heterogeneity existed on the prognostic correlations of GATA3 in pan-cancers; especially for BLCA, as the hazard ratio was <1 with a p-value <0.01." (PMID 35647011, 2022). "To investigate the roles of GATA3 mutants in cancer cell proliferation, we performed a cell proliferation assay." (PMID 35154280, 2022). "Immunofluorescence (IF) staining for the epithelial cell markers cytokeratin 5 and cytokeratin 7 and the transcription factor GATA3 was performed to characterize the three cancer organoid models." (PMID 35805961, 2022). "High GATA3 expression was adversely connected with immunological aspects such as immunomodulators, cancer immune cycles, TIICs, immune checkpoints, and TIS in the BLCA TME." (PMID 35647011, 2022). "In the Xiangya-Pingkuang cohort, GATA3 was validated to be negatively correlated with the majority of the cancer-immune cycles, especially with their vital steps, such as T cell recruiting, Macrophage recruiting, and NK cell recruiting." (PMID 35647011, 2022). "In recent years, more and more studies have shown that GATA3 is closely related to the prognosis of various cancers." (PMID 35993027, 2022). "We noticed that activities of most steps, including cancer antigen presentation, T cell priming, and immune cell recruitment, were significantly restrained in the high-GATA3 group." (PMID 35647011, 2022). "This manner of function is also reflected by that GATA3 is lost in and suppresses some cancers but promotes some others." (PMID 34595169, 2021). "Enforced expression of GATA3 in HCT116 cells inhibited a series of cancer-promoting proteins, DNMT1, SETD1A, SETDB1, FOXM1, MYC, and MSI1." (PMID 34595169, 2021). "GATA3 can also inhibit cancer metastasis and is aberrantly expressed or deleted in most patients with breast cancer." (PMID 34262865, 2021). "Strikingly, KIAA1429 preferentially induces GATA3 pre-mRNA in a targeted manner under the guidance of the antisense gene lncRNA GATA3-AS to maintain their roles in cancer progression." (PMID 35004679, 2021). "Considering their biological role, 3 LNM-upregulated genes (ATG10, GATA3 and S100B) are potential markers of aggressive phenotype and increased metastatic potential of cancer cells." (PMID 33658651, 2021). "This subgroup of tumors presents much lower positivity for typical breast markers, such as mammaglobin (17–24% positivity), GCDFP-15 (0–5%), and GATA3, which show a lower expression than that identified in luminal carcinomas or HER2." (PMID 34771579, 2021). "Negativity for epithelial markers including CK5/6, CK7, CK20, p63, CDX2, TTF1, PSA, and GATA3 helped to exclude the possibility of a carcinoma." (PMID 34449584, 2021). "In luminal A cancer, the hypomethylation enhances the commitment of luminal lineage at key lineage-specific markers (GATA3, ESR1, FOXA1)." (PMID 31529022, 2020). "In our study, T. pratense extract at all the assessed doses (100, 200, and 400 mg/kg) reduced MMP‐2 expression and ultimately inhibited the metastasis of GATA‐3‐positive cancer cells to the brain and lung." (PMID 33133558, 2020). "Gata3 has previously been reported to play a role in prostate development and in cancer progression." (PMID 32894216, 2020). "Studies showed that GATA3 not only regulates growth and differentiation of many types of malignant tumors, but also participates in the clinical classification and prognosis of malignant tumors." (PMID 32760217, 2020).